PRMT3 (protein arginine methyltransferase 3)
Diseases named in the same sentence as PRMT3 in open-access papers (continued):
Sharing a sentence is not in itself a finding about the gene and the disease.
cancer (24 papers, 2013 to 2025). A tumor composed of atypical neoplastic, often pleomorphic cells that invade other tissues. "In the kidneys, PRMT3 lacks cancer-associated interacting proteins and thus prioritizes binding to ADMA precursor proteins, generating ADMA through methylation and inhibiting NOS activity to mitigate fibrotic damage." (PMID 41583428, 2025). "In contrast, overexpression of PRMT3 reduces the amount of the ZNF277–uS5 complex, which is linked to poor prognosis in human cancers." (PMID 39964832, 2025). "It has previously been suggested that PRMT3 promotes cancer progression by reprogramming cancer cell metabolism." (PMID 41154773, 2025). "PRMT3, as a type I protein arginine methyltransferase, primarily catalyses the asymmetric dimethylation of arginine residues and plays a key role in cancer development through various mechanisms including cell metabolism and gene regulation." (PMID 39964832, 2025). "The high expression of STIP1 increased the interaction between AHCY and LDHA and then AHCY recruits PRMT3 to methylate LDHA at R106 to promote the proliferation of cancer cells." (PMID 41163796, 2025). "PRMT3 plays a significant role in gene regulation and various cellular functions, making it a therapeutic target for human cancers for a long time." (PMID 39964832, 2025). "Studies have identified abnormal expressions of PRMT3 and CARM1 in several malignancies, closely linked to cancer progression, advancement, and resistance to treatment." (PMID 39964832, 2025). "Our research results indicate that PRMT3 has a novel oncogenic role in HCC by linking post‐translational modifications with cancer metabolism, making it a promising therapeutic target for HCC." (PMID 39964832, 2025). "The type I PRMT family includes PRMT1, PRMT2, PRMT3, PRMT4, PRMT6, and PRMT8, which have been linked to various aspects of cancer development, including carcinogenesis, metastasis, and drug resistance." (PMID 39699269, 2025). "As potential targets for cancer therapy, PRMT3 and PRMT4 have shown significant research and clinical value." (PMID 39964832, 2025). "PRMT3 has been reported to be involved in several biological processes in cancer progression recently." (PMID 39256398, 2024). "Other scientists have recently discovered that the PRMT3 protein plays a vital role in chemotherapy resistance in cancer." (PMID 38911125, 2024). "PRMT3 has been a long sought‐after therapeutic target for human cancers, however, efforts to manipulate both PRMT3 activity and ADMA levels via chemical approaches have been largely unsuccessful." (PMID 39120042, 2024). "Protein arginine methyltransferase 3 (PRMT3) plays an important role in gene regulation and a variety of cellular functions, thus, being a long sought‐after therapeutic target for human cancers." (PMID 39120042, 2024). "Since PRMT1 has been more extensively studied in cancer than PRMT3, we focused on exploring the function of PRMT3." (PMID 37973560, 2023). "SGC707, a potent, selective inhibitor of PRMT3, was utilised to observe the therapeutic effect of PRMT3 pharmacological inhibition in PRMT3‐overexpressing carcinomas." (PMID 35090076, 2022). "In summary, these findings indicated that PRMT3 inhibition is a novel and potential therapeutic strategy for treatment of cancer patients." (PMID 34753906, 2021). "Further studies providing mechanistic insights into the functional roles of PRMT3 are required to explore the therapeutic potential of PRMT3 in cancers and other diseases." (PMID 33495566, 2021). "Results from western blot and ELISA assays showed that PRMT3 overexpression promotes VEGFA expression of cancer cells." (PMID 34753906, 2021). "PRMT3-overexpressing cancer cells were addicted to GAPDH-mediated metabolism and sensitive to the inhibition of GAPDH and mitochondrial respiration." (PMID 31324208, 2019). "This unique feature provides a molecular basis for the double blockade of these two metabolic pathways in attempts to kill PRMT3-overexpressing cancer cells." (PMID 31324208, 2019).
cancer (continued). "PRMT3 inhibitors represent promising therapeutic candidates for cancer and metabolic disorders." (PMID 41583428, 2025). "Moreover, studies have shown that PRMT3 is a critical regulator controlling the switch from oxidative phosphorylation to glycolysis in cancer cells, and cancer cells with high PRMT3 expression rely on glycolysis for their metabolic processes." (PMID 41583428, 2025). "Notably, we also observed a significant positive correlation between PRMT3 and PD-L1 mRNA levels across various human cancer datasets from TCGA." (PMID 40050608, 2025). "In PRMT3, this structure may influence its interaction with specific transcription factors, thereby regulating the expression of cancer‐related genes." (PMID 39964832, 2025). "The opposing effects of ZNF277 and PRMT3 expression on human cancer prognosis suggest that targeting the ribosomal uS5 may reduce the growth of human cancers." (PMID 39964832, 2025). "Moreover, the biological functions of PRMT3, particularly its non‐enzymatic functions in cancer cell lines, remain to be elucidated." (PMID 39964832, 2025). "Also, our IF staining of PRMT3 in human and mouse HCC tissues showed that PRMT3 protein expression is much higher in cancer cells than in other cell types." (PMID 39256398, 2024). "Furthermore, the biological functions of PRMT3, especially non‐enzymatic functions in cancer cell lines remains required to be clarified." (PMID 39120042, 2024). "PRMT3 may also play a role in carcinogenesis by regulating specific gene expression within cancer cells." (PMID 38911125, 2024). "PRMT3‐downregulated cancer cells were more likely to be killed by T cells." (PMID 37973560, 2023). "Collectively, these data suggested that silencing PRMT3 could inhibit the resistance of cancer cells to ferroptosis by suppressing GPX4 expression in EC." (PMID 37973560, 2023). "Furthermore, SGC707 was used to pharmacologically inhibit PRMT3 activity of cancer cells, and similar results were obtained." (PMID 34753906, 2021). "PRMT3 plays a multifaceted role in regulating immune responses and maintaining mitochondrial integrity, and its dual functionality makes it a compelling subject for therapeutic exploration in cancer, particularly in immune evasion and pro-inflammatory signaling." (PMID 41583428, 2025). "Thus, our studies suggest that PRMT3-mediated methylation of HSP60 may similarly drive therapeutic resistance to ICB in other cancer types, which will be explored in future studies." (PMID 39256398, 2024). "Moreover, silencing PRMT3 inhibited VEGFA expression of cancer cells." (PMID 34753906, 2021). "In addition, analysis using GEPIA database indicated that PRMT3 was upregulated in various cancers." (PMID 34753906, 2021). "We further demonstrated that PRMT3-mediated the methylation PDHK1 at arginine 363/368 sites, enhances its kinase activity, and thereby promoting lactate accumulation in cancer cells." (PMID 40050608, 2025). "Recent studies indicate that PRMT3 and CARM1 play significant roles in the occurrence and progression of cancer." (PMID 39964832, 2025). "Numerous studies have shown that PRMT3 and CARM1 are overexpressed or dysregulated in cancer, hence the development of potent and selective inhibitors against PRMT3 and CARM1 has attracted widespread attention." (PMID 39964832, 2025). "In GSE36376, the expressions of PRMT1, PRMT2, PRMT3, PRMT4, PRMT5, and PRMT7 were upregulated in cancer tissues." (PMID 37627211, 2023). "In cancer tissues of GSE25097, the expressions of PRMT2, PRMT3, PRMT4, PRMT5, and PRMT7 were upregulated in cancer tissues, whereas the expressions of PRMT6 and PRMT9 were downregulated." (PMID 37627211, 2023). "In GSE14520, the expressions of PRMT1, PRMT3, PRMT4, and PRMT5 were upregulated in cancer tissues, whereas PRMT2 and PRMT8 were downregulated." (PMID 37627211, 2023). "Multiple functions exerted by PRMT3 and CARM1 in various cancers." (PMID 39964832, 2025).
cancer (continued). "Our results suggested a novel oncogenic role of PRMT3 in HCC, and it could be a promising therapeutic target for HCC by linking post‐translational modification and cancer metabolism." (PMID 35090076, 2022). "Moreover, we identified a total of 293 PRMT3-interacting proteins in pancreatic cancer cells and found that PRMT3 methylated GAPDH at arginine 248 to promote glycolysis and mitochondrial respiration simultaneously in cancer cells." (PMID 31324208, 2019). "Together, our data support developing inhibitors that are selective for PRMT1 and PRMT3, but not for PRMT4 and PRMT6, to eliminate cancer persistence." (PMID 39699269, 2025).
infection (3 papers, 2010 to 2024). The state of being infected such as from the introduction of a foreign agent such as serum, vaccine, antigenic substance or organism. "Infection with HIF-1α(+) reversed the downregulated expression of HIF-1α, and OPN, and the upregulated levels of α-SMA in VSMCs in the presence of PRMT3 deficiency." (PMID 38200452, 2024).
PRMT3 also shares sentences with these, for which no sentence is quoted: dyslipidemia (2 papers); non-alcoholic fatty liver disease (2); breast adenocarcinoma (1); cardiovascular diseases (1); Dravet syndrome (1); endometritis (1); esophageal cancer (1); hyperlipidemia (1); metabolic disorders (1); multiple myeloma (1); rectum adenocarcinoma (1); skin cutaneous melanoma (1); Ureteral obstruction (1).